RNU6-429P (RNA, U6 small nuclear 429, pseudogene)
Gene: Small nuclear RNA gene on chromosome 5 (11,027,200 to 11,027,307, forward strand). Ensembl gene ENSG00000207312.
Homologues: Orthologues: chimpanzee U6 (100% identical), macaque U6 (96% identical), mouse Gm24612 (87% identical). Paralogues in human: RNU6-12P (90% identical), RNU6-13P (90% identical), RNU6-32P (90% identical), RNU6-7 (90% identical), RNU6-8 (90% identical), RNU6-1 (89% identical), RNU6-116P (89% identical), RNU6-17P (89% identical), RNU6-18P (89% identical), RNU6-19P (89% identical), RNU6-2 (89% identical), RNU6-3P (89% identical), and 1286 more.